SMAD2 (SMAD family member 2)
Diseases named in the same sentence as SMAD2 in open-access papers (continued):
Sharing a sentence is not in itself a finding about the gene and the disease.
breast carcinoma (continued). "In TMEPAI knockdown cells, even though both Smad2 and Smad3 activities are enriched, the growth of breast cancer cells is inhibited suggesting that Smad2 transcriptional activity is dominant and growth inhibitory over Smad3 in the absence of TMEPAI." (PMID 31798766, 2019). "To further investigate the clinical relationship between SMAD2 and miR-190, we examined the expression of SMAD2 in 30 specimens of primary breast cancer tissues by RT-qPCR." (PMID 29510731, 2018). "To study the relevance of the GPR50/TβRI complex on cell proliferation and tumor development we choose the MDA-MB-231 breast cancer cell line in which we were able to recapitulate the spontaneous Smad2 and Smad3 phosphorylation in the presence of GPR50." (PMID 29572483, 2018). "Overexpression of miR-190 inhibits TGF-β signaling via down-regulation of SMAD2 expression and suppresses breast cancer metastasis both in vitro and in vivo." (PMID 29510731, 2018). "The expression of miR-190 and SMAD2 in breast cancer tissues, adjacent normal breast tissues and cell lines were determined by RT-qPCR." (PMID 29510731, 2018). "Both are required to enhance sphere formation by activating the Smad2/3 pathway in breast cancer and pancreatic cancer stem cells and are thought to be involved in tumor metastasis." (PMID 30373174, 2018). "Collectively, our data support the conclusion that miR-190 targets SMAD2 to suppress TGF-β signaling in breast cancer cell lines and human breast cancer specimens." (PMID 29510731, 2018). "To corroborate that SMAD2 mediates the role of miR-190 in TGF-β-induced responses in breast cancer cells, we transfected HA-SMAD2 plasmid into MCF10A cells in addition to TGF-β stimulation and miR-190 overexpression." (PMID 29510731, 2018). "For example, overexpression of miR-206 was used to treat breast cancer cells to inhibit the downstream genes of transforming growth factor (TGF)-β, such as NRP1 and SMAD2, to reduce the migration and invasion of breast cancer cells." (PMID 28701377, 2017). "Immunoblotting revealed a significant increase in phospho-SMAD2/3 levels in lysates of 48-hr and 96-hr co-cultures of breast cancer MDA-MB-231 cells with 208F fibroblasts." (PMID 28423685, 2017). "In contrast, the PRP supplementation promotes EMT in luminal B and HER2+ epithelial breast cancer cells with the expression of metastasis markers such as Smad2 and Snail1 due to the TGF-β1 mediated pathway." (PMID 28187434, 2017). "We also found that, compared to immortalized breast epithelial cell line HBL-100, SMAD2 showed a higher expression in breast cancer cells, whereas CLDN6 had a lower expression level in these cells." (PMID 28867761, 2017). "The nuclear levels of phosphorylated Smad2/3 are reduced in high-grade tumors, and the nuclear levels of phosphorylated p38 are elevated in aggressive breast cancer." (PMID 26908052, 2016). "Our results verify the direct interaction of miR-18a and Smad2, indicating that Smad2 is a gene target of miR-18a in 4T1 mouse mammary carcinoma cells." (PMID 27641158, 2016). "We found that blocking the Smad2/3 pathway by administering SB431542 inhibited VM formation in breast cancer cell lines and xenografts." (PMID 27659524, 2016). "Smad2 and Smad3 play differential roles in executing TGFβ1 signaling resulting in either suppression or promotion of breast cancer progression." (PMID 27641158, 2016). "A novel insight regarding the molecular mechanisms of breast cancer metastasis is that EGF-induced EMT can occur via the Smad2/3-Snail signaling pathway in MCF-7 breast cancer cells." (PMID 27829223, 2016). "Researchers have investigated the specific functions of Smad2 and Smad3 inTGFβ-induced signaling in breast cancer cells invitro and in a mouse model of breast cancer metastasis." (PMID 27906182, 2016). "EGF also induced EMT and invasion of MDA-MB-231 breast cancer cells through ERK1/2-phospho-Smad2/3-Snail signaling pathway." (PMID 27829223, 2016).
breast carcinoma (continued). "Together, the current work shows for the first time that Rd treatment attenuates breast cancer metastasis in part through derepressing miR-18a-mediated Smad2 expression regulation." (PMID 27641158, 2016). "Collectively, these results clearly demonstrated that metformin and LKB1 inhibited the effect of TGF-β on phosphorylation of Smad2/3, leading to suppression of its transcription activity in breast cancer cells and in precancerous lesion." (PMID 26718214, 2016). "Using recombinant protein, as well as a synthetic peptide fragment, we demonstrate the ability of asporin to inhibit TGF-β1-mediated SMAD2 phosphorylation, epithelial to mesenchymal transition, and stemness in breast cancer cells." (PMID 26327350, 2015). "We transfected T47D human breast cancer cells with pSBE4-luc, a Smad-2/3-responsive reporter, and pRL-CMV-luc as control." (PMID 25603319, 2015). "Phosphorylation of Smad2 at the C terminus domain has been shown to suppress breast cancer cell invasion and metastases to bone in vivo." (PMID 25884855, 2015). "Once formed, Smad2/3:Gli2 complexes stimulate the expression of parathyroid hormone-related protein necessary for breast cancer metastasis to bone." (PMID 26160166, 2015). "We provide the first evidence that ZOL can affect the activin signaling pathway specifically in ER-ve breast cancer cell lines by a dual mechanism; decreasing secretion of follistatin and preventing nuclear localization of linker phosphorylated Smad2." (PMID 25884855, 2015). "In hepatocarcinogenesis, the TGF‐β effector SMAD4 appears to control the transcription of miR‐181b, whereas TGF‐β induces miR‐181a/b at the post‐transcriptional level through SMAD2/3‐dependent miRNA maturation in breast cancer." (PMID 25728313, 2015). "Taken together, our data suggested that ADC attenuates the TGF-β1-induced EMT, migration and invasion of human breast carcinoma through the suppression of Smad2/3 and β-catenin signaling pathways." (PMID 25658913, 2015). "Although Smad2/3/4 signaling plays a tumor suppressor role, it also exhibits a pro-metastatic function in breast cancer." (PMID 24550933, 2014). "Taken together, HRG-β1 induced EMT through phospho-Smad2-mediated expression of Snail via the PI3k/Akt signaling pathway in both breast cancer cell lines." (PMID 23937725, 2013). "Phosphorylation of Smad2 can be effectively switched off in breast cancer cells, MDA-MB-231, when treated with a TKRI, for as little as 1 h." (PMID 24196484, 2013). "Recently, it has been reported that D10, a neutralizing antibody directed against TGF-βRII, blocks breast cancer growth and spread in animal models via inhibition of Smad-2 phosphorylation." (PMID 23826206, 2013). "CDH5 has been shown to be induced in an EMT of mammary tumor cells, influencing the levels of Smad2 phosphorylation and upregulating the expression of TGF-β target genes." (PMID 24283570, 2013). "At least four well-known breast cancer genes including SMAD2, SMAD4, TGFB3 and TGFBR3 are involved in palate development." (PMID 23281707, 2012). "Our studies focused on the impact of CRF on SMAD2 and β catenin, being molecules involved in two central signaling pathways regulating breast cancer growth and metastasis, these of TGFβ and Wnt respectively." (PMID 20875132, 2010). "For example, activin prevents cell proliferation in breast cancer through SMAD2/3-dependent regulation of cell cycle arrest genes." (PMID 20565978, 2010). "MCF-7 breast cancer cells were co-transfected with expression plasmids of Smad2, Smad3, Smad4, or Smad4 in combination with either Smad2 or Smad3." (PMID 19943940, 2009). "The MCF-7 hormone-dependent breast cancer cell line was transiently transfected with Smad2/4 or Smad3/4 and treated with TGF-β1 for 8 hours." (PMID 19943940, 2009). "This is consistent with the previous study that suggested active Smad signalling with nuclear accumulation of phospho-Smad2 in breast cancer bone metastatic lesions." (PMID 18781153, 2008).
breast carcinoma (continued). "Furthermore, the suppression of ACC1 increases epithelial–mesenchymal transition and tumor metastasis by increasing the expression of cellular acetyl-CoA and inducing SMAD2 acetylation in breast cancer cells." (PMID 39187636, 2024). "Interrogation of a recently published SMAD2/3 ChIP-seq dataset (GSE83788) identified significant enrichment of SMAD binding within intron 1 of the C1orf106 gene locus in human breast cancer MII cells following TGF-β stimulation, suggesting it is a site of transcriptional regulation." (PMID 39329715, 2024). "In addition, OSR1 acts directly on SMAD2/3 and phosphorylates 223Thr in the SMAD2-linked region and 179Thr in the SMAD3-linked region, promoting TGF-β pathway signalling and breast cancer metastasis." (PMID 37685308, 2023). "Hence, we examined the effects of Ecliptae Herba, Que, Lut, and Wed on TGF-β1 induced p-Smad2/3 expression to appraise the function of Ecliptae Herba about regulating breast cancer through the TGF-β1 related signaling pathways." (PMID 37832105, 2023). "In addition, antrodin C was able to regulate the epithelial-to-mesenchymal transition and the metastasis of breast cancer cells via the suppression of Smad2/3 and β-catenin signaling pathways." (PMID 36979011, 2023). "A tumour suppressor role for Smad2 has been proposed in breast cancer metastasis." (PMID 37344532, 2023). "Notably, RNF12 expression strongly correlated with both phosphorylated AKT and phosphorylated SMAD2 levels in breast cancer tissues." (PMID 35013159, 2022). "Additionally, by counteracting the effects of miR‐18a and down‐regulating Smad2 expression, GRd suppresses the metastasis of breast cancer." (PMID 36127129, 2022). "Finally, we applied our model to disambiguate the roles of Smad2 and Smad3 in breast cancer disease progression from a publicly available dataset." (PMID 35858839, 2022). "Indeed, treatment with curcumin downregulates the expression of TGF-β1 which in turn inactivates molecular MMP-9 and Smad2 fibrotic markers, suppressing the growth of breast cancer cells." (PMID 36143462, 2022). "Moreover, in MCF-7 and pre-malignant 4T07 breast cancer cells treated with TβRII+ EVs, we detected higher levels of TβRII and downstream phosphorylated-SMAD2 (P-SMAD2) than in cells treated with TβRII− EVs." (PMID 35915084, 2022). "Moreover, IGFBP-3 has been shown to bind to and activate TGF-β receptor, thus leading to phosphorylation of Smad2 and Smad3 in breast cancer cells." (PMID 35798794, 2022). "Our study further proved that ER stress could inhibit 3D Matrigel‐induced VM of breast cancer cells via TGF‐β1/Smad2/3 and β‐catenin signaling." (PMID 34320274, 2021). "Additionally, epidermal growth factor (EGF) can induce EMT of breast cancer cells via the phospho-Smad2/3 Snail signaling pathway." (PMID 34422038, 2021). "TFAP2A-AS1-interfered with miR-933-mediated targeting of SMAD2 in breast cancer cells." (PMID 33511320, 2021). "Importantly, we found that opioid exposure failed to induce classical migration pathways such as MAPK/ERK, TGF-β/SMAD2/3 or WNT/β-Catenin in breast cancer cells, but activated the migratory JAK1/2–STAT3 axis." (PMID 33465556, 2021). "Their low expression level upregulates SMAD4 and SMAD2 genes in breast cancer patient samples." (PMID 34297787, 2021). "As we showed, analysis of the TCGA database revealed a prognostic role of TGFβR1 and p-Smad2 in the overall survival of breast cancer patients, and examination of breast cancer tissue samples indicated the proximity of macrophage marker CD68 and p-Smad2 in breast cancer cells." (PMID 32724475, 2020). "Interestingly, myoferlin was previously reported to regulate the TGF-β autocrine loop in breast cancer cells, and Smad2, a downstream transducer, was recently reported as a mitofusin interactor in mitochondrial fusion." (PMID 32575867, 2020).
breast carcinoma (continued). "In addition, Western blot analysis indicated that chemerin treatment inhibited the phosphorylation of SMAD2/3 in TGF-β-stimulated breast cancer cells." (PMID 32325994, 2020). "Interestingly, TrkB directly associates with SMAD2, SMAD3, and SMAD4 in breast cancer tissues and cancer cell lines." (PMID 32340410, 2020). "TRIM59 promotes neuroblastoma through the Wnt/beta-catenin and PI3K/AKT signaling pathways, accelerates bladder cancer via the TGF-beta/Smad2/3 signaling pathway, and facilitates breast cancer, cholangiocarcinoma, and ovarian cancer through the PI3K/AKT signaling pathway." (PMID 32133014, 2020). "Furthermore, the knockdown of TrkB in breast cancer cells promotes TGF-β-mediated transcriptional activation through phosphorylation of SMAD2 and SMAD3." (PMID 32340410, 2020). "In addition, SMAD2/3 also participates in lipid metabolism in mouse hepatocytes and epithelial-mesenchymal transition and metastasis induction in breast cancer." (PMID 32850796, 2020). "TGF-β/Smad signaling plays an important role in the progression of EMT in breast cancer, in which phosphorylation of Smad2 triggers the formation of a complex between Smad2 and Smad4, resulting in nuclear translocation of the Smad2/Smad4 complex and subsequent gene transcription." (PMID 32226772, 2020). "While the inactivating mutations in Smad2 and Smad3 have not been reported in breast cancer, this has been reported in Smad4." (PMID 31798766, 2019). "Although earlier inferences regarding the dual role of TGF-β in carcinogenesis have been obtained using different in vitro and in vivo models, a comparative analysis of Smad2 and Smad3 proteins allowed us to determine how such a functional switch truly occurs in breast cancer." (PMID 31798766, 2019). "Based on the results published, we hypothesized that aberrant functional expression of Smad2 and Smad3 in breast cancer contributes to the pro-oncogenic activities of TGF-β." (PMID 31798766, 2019). "There was no significant change in the expression of SMAD2 and EMT markers and cellular morphology after TGF-β stimulation, despite the overexpression of miR-190, suggesting that SMAD2 inhibition mediates the effects of miR-190 overexpression on breast cancer cell EMT." (PMID 29510731, 2018). "miR-190 suppresses breast cancer metastasis both in vitro and in vivo by targeting SMAD2." (PMID 29510731, 2018). "miR-190 antagonizes TGF-β-induced EMT by targeting SMAD2 and suppresses breast cancer metastasis." (PMID 29510731, 2018). "Most importantly, we identified a regulation of the TGFβ pathway-associated proteins TGFβ2, TβR1 and SMAD2, as well as a highly significant upregulation of previously unreported phosphorylation sites of CD44 upon TRAP perturbation in the MDA-MB-231 breast cancer cell line." (PMID 28915803, 2017). "Using a combined gene set consisting of both groups of genes, we found that promoter regions with BRCA1 mutation-associated R-loops are enriched with binding sites for breast cancer-related transcription factors, such as GATA3 and FOXA1 in LP cells and SMAD2/4 and STAT6 in ML cells." (PMID 28649985, 2017). "To analyze the GDF15-induced signaling pathways involved in tumor sphere formation, we first examined the phosphorylation of Smad2 by western blot analysis to determine whether GDF15 stimulates the Smad pathways in MCF7 breast cancer cells." (PMID 28206960, 2017). "To test this hypothesis, we blocked the SMAD2 pathway with SB431542 in two human breast cancer cell lines (MCF-7 and SKBR-3)." (PMID 28867761, 2017). "In addition, FFLZ inhibits the invasion of breast cancer cells during the EMT through suppressing the Smad2/3 signal transductions." (PMID 27830743, 2016). "However, which chemical component of PNS is pharmacologically active in suppressing breast cancer metastasis and the possible implication of miR-18a-mediated Smad2 expression regulation in this process remains to be investigated." (PMID 27641158, 2016).
breast carcinoma (continued). "The mechanism of EGF-induced EMT via activation of the Smad2/3 in breast cancer cells, MCF-7 and MDA-MB-231, remains unclear." (PMID 27829223, 2016). "Therefore, phosphorylated Smad2/3 levels were measured in stable Nodal knockdown or Nodal-overexpressing breast cancer cells to determine the effect of Nodal on the Smad2/3 pathway." (PMID 27659524, 2016). "Moreover, supernatant of zoledronic acid treated stromal cells reduced phospho-Smad2 protein levels in breast cancer cells." (PMID 26203666, 2015). "Our results demonstrate that ADC inhibits TGF-β1-induced changes in EMT markers via down-regulation of Smad2/Smad3 signaling cascades as well as inhibits matrix degradation, migration, and invasion of breast cancer cells through the inhibition of β-catenin signaling pathway." (PMID 25658913, 2015). "To test whether Cerberus-Fc can directly impact Nodal mediated Smad-2/3 signaling in Nodal expressing breast cancer cells, we performed a phospho-Smad2 Western blot." (PMID 25603319, 2015). "We therefore tested whether recombinant asporin and the synthetically produced peptide fragment were able to inhibit TGF-β1-mediated activation of SMAD2 in breast cancer cells." (PMID 26327350, 2015). "Several previous studies have demonstrated that Smad2 expression level in cancer cells appeared to be correlated with tumor development and prognosis in patients with gastric carcinoma, glioma, breast cancer, colorectal cancer, and esophageal squamous cell carcinoma." (PMID 25373709, 2014). "In this study, we investigated whether HRG-β1/ErbB3 induces the process of EMT with involvement of Smad2 activation in the ErbB2-overexpressing SK-BR-3 cell line and luminal A breast cancer cell line MCF7." (PMID 23937725, 2013). "Interestingly, the association of SMAD2/3 with RUNX2 has been reported previously in B-lymphocytes and human breast cancer cells." (PMID 19563662, 2009). "In addition, both TGF-β and Smad2 are indicators of poor prognosis in human breast cancers." (PMID 35848617, 2023). "In breast cancer cells, the reduction of the oxidative metabolism in favor of glycolytic energy production leads to the accumulation of acetyl-CoA and the consequent acetylation of the transcription factor Smad2, which is a well-known inducer of the mesenchymal genes patterns." (PMID 36945054, 2023). "IL-11 also influences breast cancer (BC)-related bone metastases, and its expression is upregulated through the Smad2/3 and p38 MAPK pathway activation by the TGF-β/TGF-βR axis." (PMID 38352248, 2023). "Smad2 knockdown increases the aggressiveness of metastatic human breast cancer MDA-MB-231 cells while Smad3 knockdown prolongs the latency and delays the growth of bone metastasis, indicating that selective targeting of Smad2 or Smad3 may result in different therapeutic responses." (PMID 27641158, 2016). "Furthermore, Rd treatment specifically increased the luciferase reporter activity of Smad2 3′-UTR containing miR-18a seed region, supporting the implication of miR-18a-mediated Smad2 regulation in the anti-metastatic effect of Rd in 4T1 mammary carcinoma cells." (PMID 27641158, 2016). "We speculate that Smad3 is more crucial than Smad2/4 for the G3BP1-induced EMT in breast cancer." (PMID 25962958, 2015). "Thus, our results provide further evidence supporting the conclusion that Nodal is expressed in invasive, poorly differentiated human breast cancers, that Nodal can induce breast cancer cell invasion and proliferation, and that Cerberus-Fc inhibits Nodal mediated Smad-2 phosphorylation." (PMID 25603319, 2015). "Therefore, we suggest that blockade of the EMT mechanisms by HRG, including ErbB3 and not only Snail but also Smad2, might be a useful therapeutic target in breast cancer." (PMID 23937725, 2013). "Therefore, we investigated whether the HRG-β1 and ErbB3 activate Smad2 signaling during process of EMT in breast cancer cells." (PMID 23937725, 2013).